PHLPP1 (PH domain and leucine rich repeat protein phosphatase 1)
Diseases named in the same sentence as PHLPP1 in open-access papers (continued):
Sharing a sentence is not in itself a finding about the gene and the disease.
Insulin resistance (5 papers, 2013 to 2022). Increased resistance towards insulin, that is, diminished effectiveness of insulin in reducing blood glucose levels. "We have previously reported insulin resistance dependent decrease in serine phosphorylation of Akt1, Akt2 and Akt3 in neuronal cells.We next proceeded to test the effect of PHLPP1 silencing on Akt isoforms in neuronal insulin signaling and resistance." (PMID 36376971, 2022). "Hepatic CB1R-induced ER stress leads to insulin resistance by upregulation of serine phosphatase PHLPP1, Lipin1, and ceramide production." (PMID 29570673, 2018). "However, insulin resistance upregulated expression of PHLPP1 by 4.2 fold (lane 1 vs. lane 3) and of PHLPP2 by 2.3 fold (lane 1 vs. lane 3) irrespective of insulin stimulation." (PMID 36376971, 2022). "In fact, it has been described that PHLPP1 overexpression induces insulin resistance." (PMID 33920886, 2021). "Taken together, these results suggest that GN might contribute to improvement of hepatic insulin resistance by inhibition of CB1R-induced PHLPP1, Lipin1, and ceramide production." (PMID 29570673, 2018). "In the present study, we report differential increase in expression of both PHLPP1 and PHLPP2, in hyperinsulinemia mediated insulin resistance in two neuronal cell lines in vitro, with or without insulin stimulation." (PMID 36376971, 2022).
cardiac arrest (4 papers, 2018 to 2023). Cessation of breathing and/or cardiac function. "In this issue of the JCI, Li and Zhu report on their engineering of a peptide (TAT-PHLPP9c) that inhibited the phosphatase PHLPP1 and increased survival in murine and rodent models of cardiac arrest." (PMID 37115696, 2023). "We reported that SCOP/PHLPP1 is increased in the hippocampus 24 h after a cardiac arrest mediated global cerebral ischemia in the rat19." (PMID 29739983, 2018).
colitis (4 papers, 2017 to 2022). Inflammation of the colon. "Murine PHLPP1-deficient Treg cells are unable to protect against colitis induced by naive CD4+ T-cell transfer." (PMID 27477328, 2017).
melanoma (4 papers, 2021 to 2023). A malignant, usually aggressive tumor composed of atypical, neoplastic melanocytes. "Nevertheless, our finding that AKT2 knockdown greatly attenuates the metastatic potential of human melanoma cell lines is consistent with previous data, suggesting that PHLPP1 inhibits melanoma metastasis by suppressing the phosphorylation of AKT2 and AKT3 but not AKT1." (PMID 37894325, 2023). "Similarly, it has been shown that the PHLPP1 phosphatase suppressed melanoma metastasis through the dephosphorylation of AKT2 or AKT3 but not AKT1 in human melanoma cells." (PMID 37894325, 2023).
diabetic cardiomyopathy (3 papers, 2020 to 2024). Diabetic cardiomyopathy is a disorder of the heart muscle in people with diabetes. "We explored the underlying function and mechanism of PHLPP1 in diabetic cardiomyopathy (DCM)." (PMID 32150791, 2020). "Activating the PI3K/AKT signaling pathway has been shown to ameliorate diabetic cardiomyopathy by inhibiting Phlpp1." (PMID 38562460, 2024). "A study has shown that inhibition of PHLPP1 can improve diabetic cardiomyopathy by activating PI3K/Akt signaling pathway." (PMID 34868398, 2021). "In summary, PHLPP1 plays an important part in the progression of diabetic cardiomyopathy." (PMID 32150791, 2020).
endometrial cancer (3 papers, 2020 to 2022). Primary or metastatic malignant neoplasm involving the endometrium (mucous membrane that lines the endometrial cavity). "Our results are the first results concerning PHLPP1 and 2 expressions in endometrial cancer." (PMID 31863623, 2020). "Expression levels of PHLPP1 and PHLPP2 mRNAs in samples of endometrial cancers and normal endometrial tissues were also analysed by RT‐PCR and correlated with clinical and pathomorphological data." (PMID 31863623, 2020).
Hyperglycemia (3 papers, 2020 to 2022). An increased concentration of glucose in the blood. "Our findings demonstrate beneficial effects of PHLPP1 deficiency in severely diabetic db/db mice preventing hyperglycemia as well as improving β-cell survival and insulin production in vivo." (PMID 35136063, 2022). "The analysis of PHLPP phosphatases mRNA expression showed that prolonged insulin stimulation of HEC-1A cells caused both in hypoglycemia and hyperglycemia conditions to a decrease in PHLPP1 and increase in PHLPP2 after 4 h stimulation and then the level was similar to in control cells." (PMID 36497428, 2022). "In hyperglycemia conditions, the downregulation of BMI1 expression caused a significant increase in PHLPP1 and PHLPP2 in both cell lines." (PMID 36497428, 2022). "Moreover, PHLPP1 down‐regulation plays a crucial role in hyperglycaemia‐induced cardiomyocyte apoptosis via activating the PI3K/AKT/mTOR pathways." (PMID 32150791, 2020). "While db/db control mice showed severe glucose intolerance, it was significantly improved in the db/db-PHLPP1−/− mice, together with a significant normalization of fasting glucose levels, indicating that PHLPP1 ablation prevents hyperglycemia." (PMID 35136063, 2022).
lung adenocarcinoma (3 papers, 2015 to 2021). A carcinoma that arises from the lung and is characterized by the presence of malignant glandular epithelial cells. "The current study directly examined the association between PHLPP1 expression and the efficacy of target therapy in human lung adenocarcinoma." (PMID 28938613, 2017). "High expression of PHLPP1 in lung adenocarcinoma highly correlated with longer survival." (PMID 28938613, 2017). "Of note, PHLPP1 still inversely correlated with the expression of p-Akt and/or p-ERK in human lung adenocarcinoma tissues." (PMID 28938613, 2017). "High expression levels of PHLPP1 and PHLPP2 were detected in 69.3% and 61.3%, respectively, of patients with lung adenocarcinoma." (PMID 28938613, 2017). "This study suggests that high expression levels of PHLPP1 predict a better survival from target therapy and a longer time of acquired resistance to EGFR TKIs in patients with lung adenocarcinoma." (PMID 28938613, 2017). "In conclusion, our study suggests that high levels of PHLPP1 might predict a better survival of target therapy and a longer time before acquired resistance to EGFR-TKI in lung adenocarcinoma patients." (PMID 28938613, 2017).
metastatic prostate carcinoma (3 papers, 2012 to 2022). A carcinoma that arises from the prostate gland and has spread to other anatomic sites.
Parkinson disease (3 papers, 2022 to 2025). A progressive degenerative disorder of the central nervous system characterized by loss of dopamine producing neurons in the substantia nigra and the presence of Lewy bodies in the substantia nigra and locus coeruleus. "This highlights the potential neuroprotective role of PHLPP1 deficiency in the context of Parkinson’s disease pathology." (PMID 41024062, 2025). "To explore the role of PHLPP1 deficiency in Parkinson’s disease (PD) mouse models, we utilized PHLPP1 knockout (KO) mice alongside wild-type (WT) mice subjected to 1-methyl-4-phenyl-1,2,3,6-tetrahydropyridine (MPTP), a neurotoxin that induces Parkinsonian symptoms." (PMID 41024062, 2025). "The present study aimed to answer this question through establishing a Parkinson’s disease (PD) model using the Phlpp1-/- and wild-type (WT) mice and testing their behavioral as well as molecular changes." (PMID 41024062, 2025). "This modulation may contribute to the neuroprotective effect observed in KO-MPTP mice, further supporting the potential therapeutic implication of targeting PHLPP1 in Parkinson’s disease." (PMID 41024062, 2025). "GSE35642 database revealed that FBOX22 is upregulated in an animal model of Parkinson’s disease (PD) via the mechanism of promoting the ubiquitination-dependent degradation of PHLPP1 to ameliorate neurotoxicity, revealing the role of FBXO22 in PD occurrence and progression." (PMID 36425318, 2022). "While inhibition of PHLPP1 protects neurons via the AKT pathway, its effects on dopaminergic neurons in the SN of Parkinson’s disease patients remain unexplored." (PMID 41024062, 2025).
Stroke (3 papers, 2018 to 2025). Sudden impairment of blood flow to a part of the brain due to occlusion or rupture of an artery to the brain. "This study identified a region on top of PHLPP1 as a locus associated with both AD and stroke." (PMID 41404293, 2025). "It is possible that by inhibiting AKT, PHLPP1 is acting in a causal pathway for both AD and stroke." (PMID 41404293, 2025). "While the stroke top hit is in the promoter of PHLPP1 and the AD top hit is on the 3’ end of the gene, eHiCA analysis shows strong chromatin interactions not only between the two top hits, but also with functional elements in six surrounding genes." (PMID 41404293, 2025). "Together these results suggest that PHLPP1 is highly expressed in brain tissues and cell types that are relevant to both AD and stroke pathophysiology." (PMID 41404293, 2025). "In line with these notions, PHLPP1 is highly expressed across brain regions, is highly expressed in AD and stroke relevant cell types, and is differentially expressed between AD cases and controls." (PMID 41404293, 2025). "The bait used for the stroke top hit is in the promoter region of PHLPP1 and shows strong chromatin interaction with the 3’ end of the gene." (PMID 41404293, 2025). "The current study nominates PHLPP1 as a potential therapeutic target shared between AD and stroke in both individuals of African and European ancestry." (PMID 41404293, 2025). "PHLPP1 is highly expressed across multiple cell types relevant to stroke and AD in humans, including neurons, OD, and astroglia." (PMID 41404293, 2025). "This suggests that both the AD and stroke loci are functionally modifying the same set of genes at and around PHLPP1." (PMID 41404293, 2025). "eHiCA demonstrated that the AD and stroke loci interact with regulatory elements in PHLPP1." (PMID 41404293, 2025). "PHLPP1 inhibits protein kinase B, which contributes to both AD and stroke pathophysiology." (PMID 41404293, 2025). "The top signal in the African ancestry stroke GWAS24 is chr18:60380912 (rs73465039, effect allele = T, other allele = G, effect allele frequency = .06, β = 0.22, P = 1.80×10−4), which shows strong support from nearby SNPs in the promoter region of PHLPP1." (PMID 41404293, 2025). "Indeed, PHLPP1 gene KO mice have decreased infarct volume after experimental stroke." (PMID 36291561, 2022). "The top hit in the European stroke GWAS24 in the chr18q21 region is chr18:60668973 (rs111345592, AF = .75, β = −0.03, SE = 0.01, P = 2.78×10−4) with strong regional support with a group of other SNPs near the 3’ end of PHLPP1." (PMID 41404293, 2025).
cardiac hypertrophy (2 papers, 2022). "Exercise-induced decrease in PHLPP-1 significantly stimulates cardiac hypertrophy through Akt, p70S6Kinase, and ERK, leading to a reduction in pathological hypertrophy, a reduction in cardiac apoptosis, and a reduction in infarct size." (PMID 36036015, 2022). "However, we examined the expression of PHLPP1 in exercise training-induced healthy cardiac hypertrophy." (PMID 36351918, 2022).
chronic lymphocytic leukemia (2 papers, 2015 to 2021). "It was suggested that reduced expression of PHLPP1 enhanced the antiapoptotic B-cell receptor signal in chronic lymphocytic leukemia B-cells." (PMID 33536540, 2021).
colon adenocarcinoma (2 papers, 2013 to 2021). "In fact, we identified a disease-associated WDR48 mutation in colon adenocarcinoma that is defective in binding and maintaining optimal PHLPP1 levels in cells." (PMID 24145035, 2013). "Among these mutations, we identified that an L580F mutation of WDR48 found in colon adenocarcinoma is defective in stabilizing PHLPP1." (PMID 24145035, 2013).
Hyperinsulinemia (2 papers, 2021 to 2022). An increased concentration of insulin in the blood. "Exogenous insulin and consequent hyperinsulinemia may activate some signaling molecules (such as PHLPP1 and Grb14) and influence hepatocyte apoptosis." (PMID 34118892, 2021).
hypopharyngeal squamous cell carcinoma (2 papers, 2015). "Patients with low PHLPP1 and PHLPP2 protein expressions have a poor prognosis and PHLPP1 was an independent prognostic factor in hypopharyngeal squamous cell carcinoma." (PMID 26463718, 2015). "It is necessary to investigate the expression patterns of PHLPP1 and PHLPP2 in hypopharyngeal squamous cell carcinomas (HSCCs) and clarify their clinical significance." (PMID 25793736, 2015).
myocardial ischemia (2 papers, 2020 to 2021). A disorder of cardiac function caused by insufficient blood flow to the muscle tissue of the heart. "It is of special significance to check this protective mechanism of AS-IV and/or HSYA treatment in myocardial ischemia-reperfusion because PHLPP-1 plays crucial roles in myocardial ischemia-reperfusion." (PMID 33381198, 2020).
osteoarthritis (2 papers, 2018 to 2019). A noninflammatory degenerative joint disease occurring chiefly in older persons, characterized by degeneration of the articular cartilage, hypertrophy of bone at the margins and changes in the synovial membrane. "A series of studies confirmed that PHLPP1 controls chondrogenesis and Phlpp1 deficiency protects against osteoarthritis progression." (PMID 29887852, 2018). "In murine tibia, Phlpp1 depletion limited osteoarthritis progression by increasing the cellular content of articular cartilage after destabilization of the medial meniscal tibial ligament." (PMID 31582730, 2019). "In line with our findings, in a post-traumatic osteoarthritis mouse model, Phlpp1 depletion protected against the progression of osteoarthritis by increasing cellular content and attenuating cartilage degradation." (PMID 31582730, 2019).
prostate tumor (2 papers, 2012 to 2013). "The AKT-inactivating phosphatase PHLPP1 on 18q21.33 has recently been identified as a prostate tumor suppressor." (PMID 23561577, 2013).
autism (1 paper, 2023). Persistent deficits in social interaction and communication and interaction as well as a markedly restricted repertoire of activity and interest as well as repetitive patterns of behavior. "Finally, we also identified a frameshift deletion variant in PHLPP1, a gene with known structural variants (18q21.2) that have been associated with intellectual disability but not with autism." (PMID 36702863, 2023).
chordoma (1 paper, 2021). Chordomas are rare malignant tumors arising from embryonic remnants of the notochord in axial skeleton. "Consistently, TRIM11 is a component in PHLPP1/AKT signaling pathway in human chordoma cells." (PMID 33613102, 2021).
colorectal adenocarcinoma (1 paper, 2022). The most common type of colorectal carcinoma. "In an attempt to determine how PHLPP phosphatases regulate lumenogenesis, we first tested the effects of depleting PHLPP1 and PHLPP2 expression in Caco-2 colorectal adenocarcinoma cells." (PMID 35997536, 2022).
escherichia coli infection (1 paper, 2019). Infection with the organism Escherichia Coli. "Here we report that deletion of the gene encoding PH domain Leucine-rich repeat Protein Phosphatase 1 (PHLPP1) protects mice from lethal lipopolysaccharide (LPS) challenge and live Escherichia coli infection." (PMID 31408005, 2019). "Since macrophages are a key cell type involved in the initial response to E. coli infection and LPS challenge, we analyzed the transcriptome of BMDMs isolated from WT or Phlpp1-/- mice before and after stimulation by the major LPS component, Kdo2-Lipid A (KLA), for 1, 6, or 24 hr." (PMID 31408005, 2019).
esophageal cancer (1 paper, 2015). A primary or metastatic malignant neoplasm involving the esophagus. "However, our current study is limited to proof-of-principle and further investigations are needed to understand the role of miR-224 in esophageal cancer and clarify how miR-224 regulates expression of PHLPP1 and PHLPP2 proteins during esophageal cancer compared to other cancer pathogenesis." (PMID 26245343, 2015).
Hypoglycemia (1 paper, 2022). A decreased concentration of glucose in the blood. "A similar effect was seen in Ishikawa cells, except that additionally, insulin stimulation also caused an increase in PHLPP1 but only in hypoglycemia conditions." (PMID 36497428, 2022). "In Ishikawa cells, insulin stimulation causes PHLPP1 and PHLPP2 to increase in hypoglycemia conditions and this effect is enhanced by PTC-209 treatment." (PMID 36497428, 2022). "In Ishikawa cells that lack PTEN protein, the role of both PHLPP1 may be more pronounced in hypoglycemia conditions." (PMID 36497428, 2022).
inflammatory bowel disease (1 paper, 2023). A spectrum of small and large bowel inflammatory diseases of unknown etiology. "Notably, three of these genes (CEPT1, PHLPP1, USP3) were reported to directly or indirectly link to inflammatory bowel disease through experimental or bioinformatics methods." (PMID 38201909, 2023).
invasive carcinoma (1 paper, 2020). A carcinoma that is not confined to the epithelium, and has spread to the surrounding stroma. "Additionally, the tumor suppressive function of PHLPP1 has been demonstrated in vivo, as Phlpp1 loss causes prostate neoplasia in mice and promotes invasive carcinoma progression in Pten+/− transgenic mice." (PMID 32630372, 2020).
ischemia (1 paper, 2023). A hypoperfusion of the BLOOD through an organ or tissue caused by a PATHOLOGIC CONSTRICTION or obstruction of its BLOOD VESSELS, or an absence of BLOOD CIRCULATION. "Cardiac muscle cells deficient in PHLPP1 are resistant to doxorubicin or hydrogen peroxide–induced injury, and animals deficient in PHLPP1 exhibit increased AKT activation and cerebral protection following ischemia/reperfusion injury." (PMID 37115696, 2023).
ischemic heart disease (1 paper, 2016). "PHLPP-1 could be a promising therapeutic interventional target for elderly ischemic heart disease patients." (PMID 27019292, 2016).
metastatic disease (1 paper, 2021). "Co‐deletion of PHLPP1 and PTEN is closely correlated with metastatic disease." (PMID 33599076, 2021).
neuroblastoma (1 paper, 2022). Neuroblastoma (NB) is the most common solid, extracranial childhood tumor. "We observed elevated expression of both PHLPP1 and PHLPP2 in insulin resistant neuronal cells (Neuro-2A, mouse neuroblastoma; SHSY-5Y, human neuroblastoma) as well as in the whole brain lysates of high-fat-diet mediated diabetic mice." (PMID 36376971, 2022).
non-small cell lung carcinoma (1 paper, 2015). A group of at least three distinct histological types of lung cancer, including non-small cell squamous cell carcinoma, adenocarcinoma, and large cell carcinoma. "MiR-141-3p was reported to promote proliferation of non-small cell lung cancer cells by PH domain leucine-rich-repeats protein phosphatase 1 (PHLPP1) and PHLPP2." (PMID 26569605, 2015).
premature ovarian failure (1 paper, 2022). "It is thus hypothesized that miRNA-190a-5p may play a role in promoting premature ovarian failure by targeting PHLPP1." (PMID 36406123, 2022).
Sepsis (1 paper, 2019). Sepsis is defined as life-threatening organ dysfunction caused by a dysregulated host response to infection. "To explore the role of PHLPP1 in acute inflammation, we examined the kinetics and outcome of sepsis-induced death caused by intraperitoneal (i.p.)injection of Gram-negative E. coli bacteria in WT and Phlpp1-/- mice." (PMID 31408005, 2019).